ALDH2 (aldehyde dehydrogenase 2 family member)
Diseases named in the same sentence as ALDH2 in open-access papers (continued):
Sharing a sentence is not in itself a finding about the gene and the disease.
melanoma (continued). "Conversely, ALDH2 expression has been shown to be downregulated in melanoma, leading to acetylaldehyde accumulation, which results in poorer prognosis." (PMID 37297001, 2023). "We found that ALDH2 expression levels were significantly downregulated in three GEO melanoma datasets (left)." (PMID 36831600, 2023). "Based on these observations, we hypothesize that ALDH2 downregulation in melanoma contributes to tumor progression." (PMID 40558540, 2025). "Furthermore, melanoma cells with acquired resistance to these inhibitors displayed further ALDH2 downregulation." (PMID 40558540, 2025). "The differences in ALDH2 gene expression were consistently reflected at the protein level, confirming the distinction between ALDH2-normal and ALDH2-low melanoma cells." (PMID 40558540, 2025). "We have previously reported ALDH2 downregulation in human melanoma tissues." (PMID 40558540, 2025). "Furthermore, we reveal that melanoma cells with acquired drug resistance exhibit further ALDH2 suppression, suggesting a potential feedback loop between ALDH2 and MAPK/ERK signaling." (PMID 40558540, 2025). "The mechanisms governing ALDH2 downregulation and inactivation in melanoma may involve multiple layers of regulation, including transcriptional control, mRNA stability, and epigenetic modulation, as previously reviewed." (PMID 40558540, 2025). "Moreover, publicly available datasets reveal significantly downregulated ALDH2 gene expression in human melanoma tissues compared to normal skin." (PMID 40558540, 2025). "Based on these findings, we categorized melanoma cell lines into ALDH2-normal and ALDH2-low groups." (PMID 40558540, 2025). "Our findings indicate that overexpressing ALDH2 may be a potential gene target for the therapies for melanoma." (PMID 38378847, 2024). "After comprehensive bioinformatics analysis, ALDH2, as a key gene of melanoma was identified." (PMID 38378847, 2024). "Survival analysis revealed a significant difference in survival rate between patients with high and low expression levels of ALDH2, which indicated the expression of ALDH2 could distinguish melanoma patients from normal people." (PMID 38378847, 2024). "Additionally, we also discovered that overexpression of ALDH2 inhibited viability, proliferation, migration, and invasion of melanoma cells." (PMID 38378847, 2024). "ALDH2 is a new gene biomarker of melanoma, which exerts an inhibitory effect on melanoma." (PMID 38378847, 2024). "Moreover, analysis of the GSE11445 dataset revealed that some patients with primary melanoma exhibited decreased expression of the ALDH2 gene compared to normal skin and melanocytic nevi (right)." (PMID 36831600, 2023). "Taken together, overexpression of ALDH2 may exert an anti-tumor function in melanoma." (PMID 38378847, 2024). "Most importantly, overexpression of ALDH2 suppressed the viability, proliferation, migration, and invasion of melanoma cells, which may contribute to the anti-tumor outcomes in the development of melanoma." (PMID 38378847, 2024). "In addition, it was determined that ALDH2 could accurately distinguish between melanoma and normal samples." (PMID 38378847, 2024). "Therefore, restoring the activity of these metabolic enzymes, particularly the ALDH2 enzyme, may be important to prevent melanoma initiation and progression." (PMID 36831600, 2023). "ALDH2-low metastatic melanoma cells exhibited intrinsic resistance to BRAF and MEK inhibitors, a phenomenon confirmed in ALDH2-KO A375 cells." (PMID 40558540, 2025). "Taken together, ALDH2, ADH1B, ALDH3A2, DPT, EPHX2, and GATM are potential biomarkers of melanoma, which have high prediction values for melanoma." (PMID 38378847, 2024). "After literature research, we chose 6 hub genes: ALDH2, ADH1B, ALDH3A2, DPT, EPHX2, and GATM, which were rarely reported in melanoma as the object of this research to explore their accuracy in the diagnosis and prediction of melanoma." (PMID 38378847, 2024).
melanoma (continued). "ALDH2 is expressed in the cytoplasm of control and PTX-treated melanoma cells (red)." (PMID 39062149, 2024). "Given the alterations observed following ALDH2-KO in melanoma cells, such as activation of the MAPK/ERK pathway, enhanced inflammatory phenotypes, and a metabolic shift towards glycolysis, we examined how ALDH2 status influences the sensitivity of melanoma cells to MAPK/ERK inhibitors." (PMID 40558540, 2025). "Nevertheless, whether ALDH2 is involved in tumor regulation in melanoma has not been fully investigated." (PMID 38378847, 2024). "It is also important to note that the effects of ALDH2 downregulation on tumor growth and drug response may be cell line-dependent and may not extend to BRAF-WT melanoma." (PMID 40558540, 2025).
cardiac hypertrophy (10 papers, 2010 to 2024). "Deficiency of ALDH2 resulted in worse cardiac hypertrophy and fibrosis in pressure overload mice both in α-LA treated group and vehicle treated group, suggesting that the attenuating-remodeling effects of α-LA are largely mediated by ALDH2." (PMID 32732978, 2020). "We also found that our mice also present an increase in cardiac hypertrophy in ALDH2*2 diabetic mice." (PMID 29677191, 2018). "It has been reported that the overexpression of NAD+‐dependent enzyme ALDH2 rescues chronic alcohol intake‐induced myocardial hypertrophy and contractile dysfunction." (PMID 28296029, 2017). "In the present study, we demonstrated a disrupted redox balance and a compensatory activation of proteasome and ALDH2 during compensated cardiac hypertrophy in SHR." (PMID 25954323, 2015). "Additionally, we blocked PKC by using an inhibitor and observed that, when HSF1 was upregulated, the role of ALDH2 and the cardiac hypertrophy gene weakened." (PMID 32626739, 2020). "Reduced ALDH2 activity was correlated with mitochondrial respiratory dysfunction {mitochondrial reserve capacity and maximal respiration }, pathological cardiac remodeling {cardiac hypertrophy and fibrosis } and cardiac dysfunction {%FS and end-diastolic pressure }." (PMID 27736868, 2016). "We used mechanical stretch to establish the myocardial hypertrophy model and observed that HSF1/HSP70 and ALDH2 in the cardiomyocytes both recorded increased expressions, indicating that there exists a correlation between HSF1 and ALDH2." (PMID 32626739, 2020). "Further in the research on cardiomyocytes in vitro, we found that, as the expression of myocardial hypertrophy gene increased, HSF1 and ALDH2 also correspondingly increased." (PMID 32626739, 2020). "Next, we used mechanical stretch to establish a pressure-stimulated myocardial hypertrophy model and discovered an increased expression of both HSF1 and ALDH2." (PMID 32626739, 2020). "In the present study, we showed that alpha-lipoic acid therapy attenuated pressure overload-induced cardiac hypertrophy and remodeling and improved the cardiac function in TAC mice via ALDH2-dependent manner." (PMID 32732978, 2020). "Recently, we found that 4HNE forms adducts with ALDH2 itself and attenuates its activity, thereby contributing to cardiac hypertrophy in a non-genetic model of type-2 DM." (PMID 27736868, 2016).
Cirrhosis (10 papers, 2016 to 2024). A chronic disorder of the liver in which liver tissue becomes scarred and is partially replaced by regenerative nodules and fibrotic tissue resulting in loss of liver function. "Taken together, despite that these patients were in a more advanced stage of cirrhosis, ALDH2-“GG” (wild type) still associated with a poorer prognosis (higher recurrence)." (PMID 31737110, 2019). "Additionally, in East Asian populations, the SNPs used for cirrhosis included variants related to ALDH2 (rs78069066) and HLA‐region (rs3129943), indicating that alcohol intake or viral hepatitis may influence the MR results." (PMID 37840448, 2024). "Heavy alcohol intake and the ALDH2 rs671 genotype (GA/AA) were associated with significantly increased incidence and risk of HCC and mortality in patients with HBV-related cirrhosis." (PMID 35877121, 2022). "Therefore, we investigated the association of heavy alcohol intake, ALDH2 rs671 polymorphism, and HBV infection with HCC development and mortality in patients with cirrhosis." (PMID 35877121, 2022). "Furthermore, heavy alcohol intake and ALDH2 rs671 polymorphism were significantly associated with increased risk of HCC and mortality in patients with HBV-related cirrhosis." (PMID 35877121, 2022). "Furthermore, heavy alcohol intake and ALDH2 rs671 polymorphism were significantly associated with increased risk of HCC development and mortality in patients with HBV-related cirrhosis." (PMID 35877121, 2022). "The latest research findings indicate a significant discovery 18: hypomethylation at the ALDH2 gene occurs in individuals with cirrhosis who engage in excessive alcohol consumption, unlike the case in those without cirrhosis." (PMID 37781509, 2023). "Moreover, we observed increased ALDH2 and ADH1A1 expression which are the enzymes responsible for metabolizing alcohol to acetate in cirrhosis." (PMID 28439208, 2016). "Moreover, when only using the SNP not related to ALDH2 and HLA region (rs12484700), cirrhosis was still positively correlated with HCC with an OR (95% CI) of 2.02 (1.50–2.72) (p < .001)." (PMID 37840448, 2024).
depression (10 papers, 2019 to 2025). "The relationship between the flushing response and depression is partially consistent with a report that the alcohol flushing genotype (ALDH2*1/*2) is associated with an increased risk of depression." (PMID 35869160, 2022). "Our results should be carefully compared with other studies on the association between inactive ALDH2 and depression." (PMID 35869160, 2022). "We aim to help fill the literature gap on the causal effect of alcohol use on depression by using genetic instruments of ALDH2 rs671 and ADH1B rs1229984 in the Mendelian randomization (MR) framework." (PMID 33193720, 2020). "This study aims to help fill the literature gap on the causal relationship between alcohol use and depression by using genetic variants of ALDH2 rs671 and ADH1B rs1229984 to instrument for alcohol use in the Mendelian randomization (MR) framework." (PMID 33193720, 2020). "Another study demonstrated that histidine triad nucleotide-binding protein 1 is involved in delaying the progression of depression by alleviating oxidative stress and apoptosis in the prefrontal cortex through the protein kinase C ε (PKCε)/ALDH2/4-HNE pathway." (PMID 40968356, 2025). "Decreased expression and activity of ALDH2 were found in a rat model of depression, together with Massive accumulation of 4-HNE and extensive apoptosis in the hippocampus and prefrontal cortex." (PMID 40968356, 2025). "A total of nine polygenic traits and genotypes are investigated in this study, including PGSs of height, body mass index, depression, time discounting, reproduction, educational attainment, risk preference, ADH1B rs1229984 and ALDH2 rs671." (PMID 34457340, 2021). "Of significance, is the downregulation of Ido1 and Aldh2 in brains from Winnie mice, given IDO1's association with exploratory behavior, cognitive function, and depression, and Aldh2's role in detoxifying ROS and ethanol metabolism, processes relevant to neurodegeneration." (PMID 39015786, 2024). "Most previous studies concerning the association of alcohol flushing and inactive ALDH2 with depression included small numbers of participants and did not adjust for alcohol intake." (PMID 35869160, 2022).
Insulin resistance (10 papers, 2012 to 2025). Increased resistance towards insulin, that is, diminished effectiveness of insulin in reducing blood glucose levels. "Based on these findings, the ALDH2 gene may influence visceral fat deposition, causing insulin resistance in males." (PMID 34439969, 2021). "On HFHSD, insulin tolerance test (ITT)showed significantly higher blood glucose levels of Aldh2 KI and HE mice than WT mice, indicating increased insulin resistance." (PMID 37749090, 2023). "In the present study, the ALDH2 mutation exacerbated HFD-induced NAFLD, including increased body weight, fat accumulation, liver injury, and insulin resistance in male mice." (PMID 34439969, 2021). "Notably, two significant genome-wide SNPs, rs662799 in APOA5 and rs671 in ALDH2, were identified exclusively in the overweight/obese group, suggesting a stronger genetic contribution to insulin resistance in this population." (PMID 40699860, 2025). "The consumption of ethanol of more than 20 times per week may increase insulin resistance in humans with normal ALDH2 genotypes; however, insulin resistance is still observed in people with the ALDH2*1/2* genotype who consume much less ethanol." (PMID 34439969, 2021). "For future work, we plan to perform related studies to verify that estrogen can activate hepatic ALDH2 in male mice and may be protective against the development of insulin resistance and NAFLD." (PMID 34439969, 2021). "The ALDH2*2 allele and gender may be associated with an increased risk for NAFLD; therefore, we explored the effects of ALDH2 and gender on NAFLD as a factor of changing gut microbiota, and the potential association with insulin resistance." (PMID 34439969, 2021).
oesophageal cancer (10 papers, 2009 to 2022). "In a meta-analysis of seven studies of 905 oesophageal cancer cases in East Asians, individuals with the ALDH2 *2*2 genotype were found to have a lower risk of oesophageal cancer as compared to those with a *1*1 genotype (OR 0.36; 95% CI 0.16, 0.80)." (PMID 35274198, 2022). "The ALDH2*2 variant allele is more common in Eastern Asian populations and confers nearly four times the risk of oesophageal cancer among drinkers compared with ALDH2*1 carriers." (PMID 34579050, 2021). "Accumulating evidence using the ALDH2‐rs671 gene variant has shown that ALDH2‐deficiency increases the oesophageal cancer risk associated with alcohol drinking." (PMID 33634874, 2021). "SNP rs886205 (A/G) located in the aldehyde dehydrogenase 2 (ALDH2) promoter is associated with esophageal carcinoma in alcohol-dependent patients." (PMID 29096698, 2017). "For example, in an early MR analysis of alcohol intake and oesophageal cancer, understanding the dual role of an ALDH2 genetic variant (used to instrument alcohol intake), which influences both alcohol intake and acetaldehyde metabolism, was essential in ensuring correct interpretation." (PMID 35274198, 2022). "Therefore, the observation of an increased risk of oesophageal cancer among individuals with a ALDH2 *1*2 genotype compared to *1*1 homozygotes suggested that the substantially elevated acetaldehyde levels in these heterozygotes likely mediated the effect of alcohol intake on oesophageal cancer." (PMID 35274198, 2022). "Two genetic variants that alter alcohol metabolism, ALDH2‐rs671 and ADH1B‐rs1229984, can modify oesophageal cancer risk associated with alcohol consumption in East Asians, but their associations with other cancers remain uncertain." (PMID 35048370, 2022). "A meta‐analysis of 31 case‐control studies involving 8510 cases showed that the ORs of oesophageal cancer comparing ALDH2‐rs671 AG vs GG genotype increased from 1.21 (0.95‐1.73) in non‐/rare drinkers to 3.79 (3.05‐4.72) in light drinkers and 6.50 (5.34‐7.92) in heavy drinkers." (PMID 35048370, 2022). "We found that the slow-acting ADH1B variant also increased the risk for oesophageal cancer, regardless of ALDH2 variant." (PMID 26229204, 2015). "Previous studies have shown that the ALDH2‐rs671 AA and ADH1B‐rs1229984 AA and AG genotypes were associated with lower oesophageal cancer risk compared to the GG genotype, and that ALDH2‐rs671 genotype may modify the relationship between alcohol intake and oesophageal cancer risk." (PMID 35048370, 2022). "Compared to ALDH2‐rs671 GG genotype, AG genotype was associated with significantly higher risks of IARC alcohol‐related cancers (1.30 [1.11‐1.52]) and oesophageal cancer (2.07 [1.58‐2.71]) in male ever‐regular drinkers but not in never‐regular drinkers." (PMID 35048370, 2022). "We selected data for lung (522 samples) and liver (422 samples) cancers in which the differences between ALDH2 and XRCC1 mRNA levels were pronounced and compared these data to oesophageal cancer (186 samples) in which XRCC1 and ALDH2 mRNA levels were very close." (PMID 30088263, 2018). "A recent report from China demonstrated differences in the frequency of ADH2 and ALDH2 genes between alcoholic patients who developed alcoholic cirrhosis and those who developed oesophageal cancer but no similar data are currently available for French patients." (PMID 20069042, 2009). "Interestingly, we found that the ALDH2 mRNA levels have no prognostic value in oesophageal cancer." (PMID 30088263, 2018).
pancreatic cancer (10 papers, 2011 to 2025). "Consistent with that study, our results also showed no independent association between the polymorphisms of ADH1B and ALDH2 and pancreatic cancer risk." (PMID 34267279, 2021). "The major strength of the current study is that it is one of the few studies that assessed the combined impact of ADH1B and ALDH2 polymorphisms on the association between alcohol use and pancreatic cancer." (PMID 34267279, 2021). "Due to the very limited number of studies on the effect modification of the ALDH2 polymorphism on the association between alcohol drinking and pancreatic cancer, more investigations are needed." (PMID 31510046, 2019). "Although studies generally did not support a positive association between low to moderate levels of alcohol consumption and pancreatic cancer, East Asians may be more susceptible to the carcinogenic effect of alcohol due to a highly prevalent single nucleotide polymorphism (SNP), ALDH2 rs671." (PMID 34267279, 2021). "ALDH2 is a gene that plays an essential regulatory role in alcohol metabolism and was also reported important in initiation of cancer progression of CRC and pancreatic cancer." (PMID 35178443, 2022). "In conclusion, our study did not support an association between alcohol use and pancreatic cancer even after considering the level of alcohol use and the influence of ADH1B and ALDH2 polymorphisms." (PMID 34267279, 2021).